IL10 (interleukin 10)
Diseases named in the same sentence as IL10 in open-access papers (continued):
Sharing a sentence is not in itself a finding about the gene and the disease.
lymphoma (continued). "As a kind of immunosuppressive cytokine, IL-10 participates in suppressing the activity of antivirus immune cells involving NK cells and macrophages, and it has been widely reported to be expressed in EBV-positive lymphomas, which hinder virus clearance and facilitate EBV proliferation." (PMID 36189344, 2022). "However, there are also lymphoma cases with low IL-10 levels or non-lymphoma cases with elevated IL-10 levels." (PMID 36059608, 2022). "The elevated CSF IL-10 level suggested that the patients may have already developed subclinical lymphoma in the CNS, which was not substantiated using MRI or CSF examination." (PMID 34249763, 2021). "IL-10 expression did not significantly differ between subtype infection profiles but did show a marked increase—accompanying decreased CD4:CD8b ratio—in a koala with lymphoma and co-infected with KoRV-A and -B, thus suggesting immunosuppression." (PMID 33316950, 2020). "However, as might be expected based on previous research in koalas, the KoRV-A- and B-positive koala with lymphoma that died in this study showed a markedly decreased CD4:CD8b ratio and markedly increased IL-10 expression." (PMID 33316950, 2020). "Also, we found an evidence for the diagnostic utility of the following markers: MCP-1, eotaxin, IL-10 and IL-6 for NHL and HL and IL-1β for HL, while TNF-α has limited utility due to the poor ability to discriminate amongst patients with lymphoma and healthy control, as well as IL-1β for NHL." (PMID 30814315, 2019). "In addition extremely high concentrations of IL-10 were detected in vitreous fluids from intraocular malignant lymphoma patients in this system (data not shown), in support with previous findings." (PMID 19997642, 2009). "Although the etiology for the development of lymphoma in this extranodal site remains unclear, PCNSL patients are known to be characterized by high IL‐10/IL‐6 ratio in the cerebrospinal fluid (CSF), and it may be speculated that PCNSL is derived from B cells with IL‐10‐producing capacity." (PMID 27709813, 2016). "BCAT1 inhibition blunted BCR/TLR9, but not CD40L/IL4-triggered B-cell proliferation, IL10 expression and BCR/TLR pathway-driven lymphoma xenograft outgrowth." (PMID 38854072, 2024). "The levels of IL-10 and TNF-α for the patient without lymphoma (26.3, 257 pg/ml) were lower than those of all samples involved in the study." (PMID 35928372, 2022). "Three RSV concentration levels were subjected to isolated lymphocytes from blood samples of Hodgkin lymphoma (HL), non-Hodgkin lymphoma (NHL), and without lymphoma to estimate the change in TNF-α and IL-10." (PMID 35928372, 2022). "Various studies examining non-infectious SIRS revealed significantly higher IL-10 concentrations in dogs with IMHA, acute pancreatitis, and lymphoma, but no relevant increase was found in dogs with acute trauma despite a simultaneous pro-inflammatory profile." (PMID 34222394, 2021). "IL-2 was not quantifiable in cultures of patients with lymphoma or EBV+HIV+, and IL-10 was only detectable in 15/55 (27%) patients." (PMID 30337929, 2018). "In lymphoma isolated cells treated with RSV, irrespective of doses, whenever there was a decrease in one cytokine (e.g., TNF-α), there was an increase in the level of the other (e.g., IL-10) and vice versa." (PMID 35928372, 2022).
co-infection (139 papers, 2008 to 2026). "EBV coinfection intensified this phenotype, being associated with elevated levels of IL-6, IL-10, IL-15, TNF-α, and sCD40L, and with greater loss of memory cell subpopulations." (PMID 41929504, 2026). "Inversely, Macrophage Stimulating Protein/Receptor d'Origine Nantais (MSP-RON) signaling, a pathway commonly associated with M2 macrophage differentiation, and IL-10 signaling were significantly induced by HCMV in the co-infection setting." (PMID 40980889, 2025). "Here, we show that Plasmodium-induced IL-10 also enhances susceptibility to Sp co-infection and also demonstrated that Plasmodium infections can impair innate immunity to bacterial infections independent of HO-1 and IL-10." (PMID 32714882, 2020). "A chronic co-infection of Brazilian children aged between 4 and 11 years with A. lumbricoides and T. trichiura was associated with an acute production of IL-10 in response to stimulation with A. lumbricoides antigen." (PMID 29970128, 2018). "Furthermore, helminth co-infection is associated with more advanced disease in tuberculosis patients and with reduced production of IFNγ but increased IL-10." (PMID 36753434, 2023). "P. falciparum/intestinal protozoa co-infections were associated with an enhanced IL-10 response." (PMID 35421083, 2022). "The higher IL-10/TNF-α ratio in the group of participants with Plasmodium mono-infection than in the group with Plasmodium/helminth co-infection suggests a possible lower risk of developing clinical signs in the case of STH/P. falciparum co-infection, as demonstrated by Frosch & John." (PMID 35421083, 2022). "Thus, combined IL-6 and IL-10 measurement might be clinically valuable for early identification of SMPP cases at risk of co-infection, facilitating timely intervention and improved patient outcomes." (PMID 40487016, 2025). "Furthermore, our ROC curve analyses of inflammatory biomarkers—particularly the combined use of IL-6 and IL-10—provided novel and valuable diagnostic insights, significantly improving the predictive accuracy for detecting severe cases complicated by co-infections." (PMID 40487016, 2025). "Therefore, it is possible that co-infection could either augment or diminish Treg responses and the levels of associated IL-10 observed compared to each pathogen alone." (PMID 25474738, 2014). "The presence of these co-infections was associated with significantly elevated inflammatory markers, including WBC count, LDH, IL-6, and IL-10, indicating more intense inflammatory responses." (PMID 40487016, 2025). "IL-6 and IL-10 are increased in kala-azar and HIV co-infection, while IL-6 is associated with severity signs and with the fatal outcome, similar to what is described in individuals with kala-azar without HIV." (PMID 41003560, 2025). "For instance, IL‐12 production in the co‐infection group was approximately 35%–45% lower than that induced by the Y strain alone, while IL‐10 levels were significantly elevated compared to the negligible amounts seen with the Y strain at 96 h." (PMID 40940710, 2025). "Our further ROC analysis confirmed that IL-6 and IL-10, individually and especially in combination, exhibit high sensitivity (>80%, and approximately 94% combined) for detecting co-infections." (PMID 40487016, 2025). "The observed elevated IL-10 in dogs, which were positive for anti-E. canis and anti-A. phagocytophilum IgG antibodies in mono-infection and co-infection, showed the potential role of cytokine in the host’s immune response to foster recovery from infection." (PMID 39770719, 2024). "Participants with TB-HIV co-infection had significantly higher levels of IL-10 than those infected with TB only (p = 0.028)." (PMID 38962334, 2024). "Tick-borne pathogen co-infection status showed positive effects on percent IL-10+ and PD-1+ CD4+ T cells, with posterior probabilities of being positive of 0.806 and 0.786, respectively." (PMID 38335163, 2024).
co-infection (continued). "The co-infection has also been reported to inhibit the immune response by stimulating IL-10 production, inhibiting IFN-γ secretion, weakening liver function, and promoting HBV proliferation, thereby leading to fibrosis and cirrhosis." (PMID 36638133, 2023). "Further, TNF-α, IL-1β, and IL-10 levels correlated with ALT suggesting a role in liver damage in the setting of co-infection." (PMID 37877022, 2023). "Interleukin-10 was significantly depleted by T.b.r or S. mansoni infections and further depleted due to coinfection." (PMID 37954132, 2023). "The expression of IL-13 was predominant in dogs infected with D. repens, and the expression of STAT6 and regulatory IL-10 predominated in dogs with co-infection." (PMID 36739305, 2023). "Altogether, our findings suggest that IL-10, IFN-γ, and TNF-α are key cytokines as high levels of IFN-γ and TNF-α contributed to the lethality of disease and IL-10 acted as a protector in the course of B. microti and P. berghei co-infection." (PMID 37492527, 2023). "Co-infected mice exhibited decreased levels of pro-inflammatory cytokines (i.e., IFN-γ, TNF-α, and IL-12p70), whereas the level of anti-inflammatory cytokine (IL-10) was elevated in the acute phase of co-infection." (PMID 37492527, 2023). "Production and release of TNF-α, IL-6, and IL-10 protein 24 h after B. burgdorferi infection and coinfection was confirmed via ELISA." (PMID 37764937, 2023). "IL-13 expression was predominant in dogs infected with D. repens, and STAT6 and IL-10 predominated in dogs with co-infections." (PMID 36739305, 2023). "In the S. mansoni-infected patients, serical levels of IL-10 showed a significant (p < 0.05) increase (3.59 pg/mL of mono-infection vs. 3.11 pg/mL of co-infection) compared to the control group (0.63 pg/mL)." (PMID 37243099, 2023). "The high IL-10/TNF-α and IL-10/IL-6 ratios observed here in participants with helminth co-infections are consistent with such observations." (PMID 35421083, 2022). "For example, in a co-infection model of Py and Salmonella typhimurium (St), Py line N67 infection exacerbates St burden, an effect that is lessened by blocking IL-10 on days 7–11 post-Py infection." (PMID 35631044, 2022). "M(IL-4) resulted in increased IL-4 when infected with only the G strain and reduced IL-10 during co-infection." (PMID 36389843, 2022). "This study evaluated the regulatory effect of single- and PDCoV/PEDV co-infection on regulatory cytokines (IL10, IL22, IL23, and IL33)." (PMID 36376395, 2022). "In this study, we additionally report the regulation of proinflammatory (IL1-α, IL1-β, IL6, IL8, IL18, and TNF-α) and regulatory (IL10, IL22, IL23, and IL33) cytokines associated with single-PDCoV and -PEDV infection, as well as PDCoV/PEDV co-infection." (PMID 36376395, 2022). "In rural areas, higher IL-10 concentrations were found in plasmodial-infected subjects than in those with P. falciparum/intestinal protozoa co-infection (P = 0.0007)." (PMID 35421083, 2022). "Although both Il6 and Il10 were increased in the GAS and IAV+GAS group, respectively, only co-infection caused a significant secretion of the protein products." (PMID 36365071, 2022). "The median TNF-α level and IL-10/IL-6 ratio were higher in subjects with STHs (p = 0.09) and P. falciparum-intestinal protozoa co-infection (p = 0.04), respectively." (PMID 35421083, 2022). "Co-infection led to a predominant inflammatory milieu, with reduced IL-10 and TGF-β, and/or promotion of IFN-γ and IL-1β release." (PMID 36389843, 2022). "In this study, there was a significant decrease in the expression of IL-4 and IL-10 in patients with HIV/TB co-infection compared to patients with HIV monoinfection and TB monoinfection before ART." (PMID 34835417, 2021). "IL-10 plays an important regulatory role during L. sigmodontis infection, and is involved in suppressing cerebral malaria during L. sigmodontis co-infection." (PMID 35140712, 2021).
co-infection (continued). "In our previous study, we observed an increased level of IL10 in P. falciparum and N. americanus co-infection, which significantly decreased after successful albendazole, treatment." (PMID 33832450, 2021). "In particular, the group infected with PPRV followed by GTPV was the most significant, but compared with the group infected with GTPV alone, the mRNA expression levels of TNF-α, IL-6, and IL-10 in all co-infection groups were inhibited." (PMID 33827620, 2021). "Compared with the group infected with PPRV alone, the mRNA expression levels of TNF-α, IL-6 and IL-10 were enhanced in all co-infection groups." (PMID 33827620, 2021). "Another reported decreased IFN-γ and increased IL-10 in unstimulated PBMC cultures of adults with HTLV-1-helminth co-infection versus with HTLV-1 alone, as well as decreased HTLV-1 proviral load in PBMCs of those with coinfection." (PMID 34015063, 2021). "Polyfunctional ex vivo restimulation followed by ICS revealed that on day 6 and 9 after IAV (co)infection, the frequencies of Foxp3+ Tregs producing IL-10 were significantly increased in the lungs of (co)infected compared with Mtb-alone-infected mice." (PMID 30998505, 2019). "Significant positive correlations were identified between IFN-γ verses TNF-α and IL-6 verses IL-10 in co-infection (Spearman’s P < 0.05)." (PMID 31687034, 2019). "In our severe model, IFN-γ and IL-1β were upregulated, while IL-10 was down-regulated during co-infection in IL-6−/− mice." (PMID 32038632, 2019). "Significant positive correlations were observed between IFN-γ with TNF-α (Spearman r = 0.847) and IL-6 with IL-10 (Spearman r = 0.557) among co-infection." (PMID 31687034, 2019). "Coinfection was hallmarked by extremely elevated concentrations of IL-10, as well as heightened levels of CCL2, in comparison to the distinct clinical presentations of P. vivax infections or HBV monoinfection." (PMID 31233500, 2019). "In this study, a positive correlation between IL-6 and IL-10 elevated levels during co-infection was observed." (PMID 31687034, 2019). "This suggests that the retrovirus co-infection and the upregulation of IL-10, with a potential polarization to a Treg cell profile, did not impair Th17 immunity." (PMID 30500849, 2018). "Distinct upregulation of IL-10 was also present during co-infection compared to Eimeria mono-infection at 48 and 72 hpi." (PMID 30081942, 2018). "In nematode–Plasmodium co‐infection, L. sigmodontis induced an anti‐inflammatory IL‐10 response in the co‐infected host, which counteracted the Th1 response and protected the host from ECM." (PMID 29113976, 2018). "This review briefly discusses patterns of selected cytokine (IL-6, IL-8, IL-10, TNF-α and INF-γ) responses associated with infections caused by Plasmodium, intestinal parasites as well as a Plasmodium-helminth co-infection." (PMID 29970128, 2018). "The levels of IL-6, IL-10 and G-CSF were elevated in mono-infection and increased further in co-infection." (PMID 29736763, 2018). "In vivo, it was demonstrated that mRNA expression of IFN-γ, IL-12 and IL-10 was distinctly upregulated in the ceca of chickens at the early stage of co-infection with T. gondii and Eimeria spp." (PMID 30081942, 2018). "Decreased levels of IFN-γ, TNF, IL-6, and IL-10 were observed in the serum of co-infected groups, demonstrating a modulation of Malaria immune response by Leishmania co-infections." (PMID 27446022, 2016). "Increased IL-10 expression in co-infection mice thus prompted us to determine inducible nitric oxide synthase (iNOS) expression and NO levels in lung tissue." (PMID 26913029, 2016). "The blockage of the IL-10 receptor completely abrogated the Tat effect in promoting the intracellular growth of Leishmania, thus corroborating the notion that IL-10 is an essential effector of the Tat-PKR axis during co-infection." (PMID 26608746, 2015). "Our data also suggest that IL-10 is an important mediator of these inhibitory effects for filarial co-infections." (PMID 25211342, 2014).
co-infection (continued). "Since Treg are significant sources of T cell-derived IL-10, the impact of co-infection on Tregs was assessed." (PMID 25474738, 2014). "During human co-infection with S. stercoralis and HTLV-1, increased production of interferon-γ (IFN-γ) and interleukin-10 (IL-10) is associated with decreased production of interleukin 5 (IL-5) by peripheral blood mononuclear cells (PBMCs)." (PMID 25499310, 2014). "IL-10 production by macrophages was also an essential determinant of susceptibility to systemic infection, suggesting that in the context of co-infection, macrophages both produce and respond to IL-10." (PMID 24787713, 2014). "Single nucleotide polymorphism of TNF-α and IL-10 genes studied in healthy controls and patients with HIV-HCV coinfection." (PMID 23840511, 2013). "The comparison of immune variables between single and co-infection showed higher neutrophils (P<0.0001) and a tendency for higher IL10 (P = 0.058) in co-infected compared to single infected hosts." (PMID 22253585, 2012). "IL-10 concentration was highest in HIV/HCV co-infection group when compared with the other three groups, but it was only shown a statistical raise when compared with healthy control group (p < 0.01)." (PMID 22533731, 2012). "In young sexually active adolescent women diagnosed with co-infection of oncogenic human papillomavirus and CT, IL-4 transcripts correlating to IL-10 have been detected in cervical samples." (PMID 19698128, 2009). "Similarly, IL‐10 production in the co‐infection group was maintained at a moderate level, higher than the late response of Y strain but not reaching the sustained increase seen with G strain alone." (PMID 40940710, 2025). "Compared to the non-severe group, more frequent underlying condition, wheezing, and seizures, as well as higher fever peak were observed in the severe group, with higher levels of leukocyte count, NLR, CRP, PCT, IL-6, IL-10, D-dimer, and more frequent co-infection (all P < 0.05)." (PMID 39114651, 2024). "The observed elevated IL-10 in dogs, which were positive for anti-E. canis and anti-A. phagocytophilum IgG antibodies in mono-infection and co-infection, showed the potential role of this cytokine in the host’s immune response to foster recovery from infection." (PMID 39770719, 2024). "In piglets treated with the orally administered engineered strain, the levels of IL-1β, IL-6, and IL-10 in the co-infection group were lower than those in the challenge group, indicating that the inflammatory response caused by PEDV was milder in the co-infection group." (PMID 38430229, 2024). "In the present study, the levels of IL-2, IL-6 and TNF-α were markedly higher, while the level of IL-10 was markedly lower in HIV/HBV coinfection group than those in HBV infection group and control group, suggesting that HIV worsens HBV-induced inflammatory response." (PMID 38357144, 2023). "Furthermore, compared with ICU-acquired infection patients, co-infection group had a significantly higher levels of serum IL-6 (9.58 [6.02–54.61] vs. 0.00 [0.00–29.64], p = 0.022) and IL-10 (34.37 [12.79–693.04] vs. 9.86 [2.79–44.64], p = 0.034)." (PMID 38249419, 2023). "In addition, we found that the ICU patients with co-infection had significantly higher levels of IL-6 and IL-10 than those with ICU-acquired infection." (PMID 38249419, 2023). "Moreover, patients have extreme elevations of HHV-8 viral load and IL-6 level; it has been reported that in HIV/HHV-8 coinfection, IL-4, IL-6, and IL-10 levels are increased." (PMID 35053573, 2022). "The involvement of UV light (since lesions occur in sun-exposed areas), malnutrition, and coinfection could further drive the Th2 responses with elevated levels of Treg cell population and IL-10 production in the skin." (PMID 32614818, 2020).